CD163 (CD163 molecule)
Diseases named in the same sentence as CD163 in open-access papers (continued):
Sharing a sentence is not in itself a finding about the gene and the disease.
tumor (continued). "Both methods were carried out in the same tumours, but the percentage of CD163-positive cells detected by four-colour flow cytometry analysis did not correlate directly to the number detected by IHC." (PMID 32070062, 2020). "The survival outcomes were significantly worse when CD163 and tumor immune checkpoint molecules was concurrently high." (PMID 32756500, 2020). "While nearly all MDCs were CD68+ for all cell lines, the percentage of CD163+ cells differed across the tumor lines." (PMID 33069212, 2020). "CD68+ macrophages are usually activated during antigen presentation and inflammatory responses, while CD163+ macrophages have a large number of anti-inflammatory cytokines that contribute to immunosuppression and promote tumor development." (PMID 32528967, 2020). "The significant difference also existed between the expression level of CD163 in the margin and that in tumor tissues, and the expression of CD163Tissue was much higher than that of CD163Margin (p < 0.0001)." (PMID 33178603, 2020). "Results show that tumours from patients with rs22(GC)+rs29(TC) genotype had significantly more CD163+ Mɸ (median 3.19–6.14 fold) compared to rs22(CG), rs22(CC), rs22(GG) and rs22(CC)+rs30(AG) genotypes." (PMID 32882831, 2020). "CD163 protein was positively expressed in both the tumor tissues and the invasive margin near adipose tissues." (PMID 33178603, 2020). "This feature is related with the function of CD163, and its involvement in pro-tumor switch of macrophages in cancer progression in humans and mice." (PMID 32214052, 2020). "In contrast, VAP-1 expressed in neighboring locations with CD163+ M2 macrophage was identified from tumor milieu." (PMID 32349342, 2020). "Subsequently, we co-cultured FOXO1(+) tumor cells with M0 macrophages in the presence of the anti-CSF-1 antibody and found that a percentage of the CD163+/CD68+ macrophages was significantly reduced." (PMID 33052231, 2020). "Next, we generated differential gene expression plots between CD68 or CD163 high and low tumor samples." (PMID 32809114, 2020). "A switching of the tumor microenvironment from an immune suppressive to a more reactive condition appears also supported by the finding that pro-tumorigenic M2 macrophages (CD163+ cells), although slightly increased at T18, appeared clearly reduced at T48." (PMID 33072126, 2020). "One study used tissue microarrays to assess infiltration of TAMs by CD163 staining in tumor samples from patients with localized disease, stage 4 or metastatic disease, and stage 4S disease." (PMID 32983125, 2020). "When the TME and tumor were compared, the study showed that CD3, CD45RO, V‐domain Ig suppressor of T‐cell activation (VISTA), and CD163 were enriched in TME relative to tumor." (PMID 33251010, 2020). "Another independent study also showed higher frequencies of CD163+ macrophages in tumor-infiltrating cells from resected tumors than in peripheral blood immune cells." (PMID 33363016, 2020). "In contrast, in 108 patients with BC (UK cohort) who received NAC (capecitabine plus docetaxel preceded by adriamycin and cyclophosphamide), high levels of CD163+ TAMs significantly correlated with a pCR both in tumor and metastatic axillary LNs." (PMID 33194645, 2020). "The correlation of CD68+ and CD163+ macrophage infiltration with pathological features of the tumour was determined using Spearman’s correlations and Wilcoxon rank-sum tests." (PMID 32843682, 2020). "In particular, CD163-positive M2 macrophages play a role in promoting tumor development by suppressing antitumor immunity." (PMID 32756500, 2020). "More MBC samples demonstrated CD163+ cells in the stroma (96.3% vs. 79.8%, p = 0.0468) and positive PD-L1 expression in tumor cells (29.6% vs. 10.1%, p = 0.0133) compared to TNBC samples." (PMID 31937323, 2020). "As for CD163 in the tumor margin, the HER2 subtype had the highest expression level, and a similar condition was observed in the expression level of CD163 in the malignant tissue." (PMID 33178603, 2020).
tumor (continued). "Clinical studies showed that CD163+ macrophages in tumor stroma positively correlated with poor histological grade, larger tumor size, Ki67 positivity and LN metastasis in patients with BC." (PMID 33194645, 2020). "We used multi-IF analyses to confirm that PD-L1+CD163+ TAMs were located mostly within the tumor stroma, and in patients with necrosis, PD-L1+CD163+ TAMs were observed within necrotic tissue." (PMID 33457428, 2020). "The total frequency of ISG15+ CD163+ cells in suspension of NPC tissues varied from 1% to 9.7% among all live cells in the tumor microenvironment." (PMID 33424843, 2020). "CD68 and CD163 positive macrophages were predominantly detected in the tumor stroma and intervening space between tumor cells." (PMID 33228719, 2020). "In tumor biopsies of patients, reduced CD163+ M2-TAMs was inversely correlated with the increased CD8+/CD4+ T cells ratio." (PMID 32103760, 2020). "This study thoroughly investigated the clinical relevance of TAM infiltration in OSCC, jointly evaluating CD68 and CD163 expression in both the tumor nests and surrounding stroma." (PMID 32630659, 2020). "Lastly, a recent paper shows IFITM3 is correlated with the inhibitory immune checkpoint receptors PD-L1, B7-H4, VISTA, IDO, and the tumor associated macrophage markers CD68, CD163, and CD206, which are associated with tumor immunosuppression." (PMID 33364194, 2020). "Results show that tumours from patients with the SNP combination rs22(GC)+rs30(AG) had significantly more CD163+ Mɸ (median 2.28–2.56 fold) compared to rs22(GC)+rs29(TC) and rs22(CC)." (PMID 32882831, 2020). "In the same study the infiltration of higher numbers of CD68+ or CD163+ macrophages in tumor stroma in BC patients didn’t depend on the OS, while infiltration in tumor nest was higher in patients with unfavorable OS." (PMID 33194645, 2020). "We found that PD-L1 expression was detected in 33.33% (27/81) of all the patients, mostly exhibiting a stroma-only pattern and that it was positively associated with tumor-infiltrating immune cells (CD4+, CD8+, and CD163+)." (PMID 33457428, 2020). "These cells are characterized by positive CD163 expression and orchestrate tumor evasion from immune surveillance by anti-inflammatory cytokine signaling." (PMID 32658932, 2020). "Stromal/tumoral expression of CD68 and CD163 was evaluated, as well as possible relationships with the expression of CSCs markers and tumor PD-L1." (PMID 32630659, 2020). "Initially we documented the location of CD163+ macrophages, finding a higher number of macrophages on the edge of the tumour nests." (PMID 33149188, 2020). "We decided to study CD163 in a broader context, comprising both the tumor microenvironment and circulation of CRC patients." (PMID 32824692, 2020). "CM from both tumor cell lines induced M2 polarization as shown by the increased expression of CD163, FN1, and IL10 mRNAs, and a dramatically reduced expression of these M2 markers was observed in the ezrin-depleted cells." (PMID 33086476, 2020). "Clinicopathological variables were stratified base on the tumor expression of CD163, PD-1, and LAG-3." (PMID 32756500, 2020). "In fact, HT was associated with the increased counts of CD8+ and CD138+ cells within tumor area whereas mast cells and CD163+ cells counts were comparable with those in patients without HT." (PMID 31938743, 2020). "High infiltration of CD163+ TAMs in both tumor and stroma was strongly and significantly correlated with the absence of NANOG expression." (PMID 32630659, 2020). "Clinically, ISG15+ CD163+ TAMs related to impaired survival of patients and advanced tumor stage of NPC." (PMID 33424843, 2020). "BRAF mutated tumours showed higher fractions of PD-1+ T cells, B cells and CD163+ macrophages compared to BRAF wild type tumours." (PMID 33228141, 2020). "Since TAMs have an M2 macrophages phenotype, we checked the M2 marker (CD163) in the primary tumor site, surgical margin and peritoneum by IHC staining." (PMID 31632482, 2019).
tumor (continued). "Genetic or nanoparticle-mediated ablation of CD163+ TAMs in melanoma leads to sustained tumor regression, partly through cytotoxic T lymphocyte recruitment and activation." (PMID 31611871, 2019). "The tumour samples were stained for inducible nitric oxide synthase (iNOS, M1 marker), CD163 (M2 marker), FoxP3 (Treg marker), CD47 and IDO1." (PMID 31358801, 2019). "Using immunohistochemistry, we examined tumor-infiltrating CD68+ pan-macrophages (CD68+ M) and CD163+ M2 macrophages (CD163+ M2) and tumor expression of CD47 and PD-L1 proteins in 106 cases of PDAC." (PMID 31771616, 2019). "Macrophages present in tumours (tumour-associated macrophages or TAMs) exhibit M2 phenotype and are capable of expressing CD68 and CD163." (PMID 31186031, 2019). "In comparison, an antibody to CD163, a marker for macrophages with an immunomodulatory phenotype, labeled many more cells, including cells that surrounded or infiltrated the tumor foci." (PMID 31434729, 2019). "Intriguingly, periostin facilitates the recruitment of CD163+ M2 macrophages, which potently induces immune tolerance and promotes tumor progression." (PMID 30621220, 2019). "On the basis of previous studies, we add some new Kazakh ESCC samples and found that CD163-positive TAMs were primarily located in the tumour stroma, and a few were also distributed in the tumour islet." (PMID 31186031, 2019). "CD163+ cells were detected diffusely all over the tumor and connective tissue area, while CD204+ and CD206+ cells were mainly detected in/around the tumors." (PMID 31601953, 2019). "Some studies have suggested that PD-L1-positive tumors had prominent immune cell infiltration in CCA, such as CD3+ TILs (represent overall T cells), CD8+ TILs (represent cytotoxic T cells), and tumor-associated macrophages (TAMs) (CD68+, CD163+)." (PMID 31620360, 2019). "Positivity for iNOS, CD163, and IDO1 was detected in a subset of tumour-associated macrophages (TAMs), while iNOS and IDO1 positivity was also seen in a subset (83% and 20%, respectively) of tumour cells." (PMID 31358801, 2019). "• For the whole tissue samples as well as for the tumor subregions, correlation coefficients for the CD163 staining are slightly larger than for CD14 staining for all surveyed methods." (PMID 31303867, 2019). "In order to consider the induction of CD163 expression by apoptosis we compared the conditions of equal apoptotic tumor cell fractions with CD163 expression." (PMID 31413815, 2019). "CD163 identify the M2-polarized macrophages, which are highly versatile cells known to influence multiple steps in tumor development and invasiveness along with angiogenesis and immunosuppression." (PMID 31649675, 2019). "M2-macrophage traits in tumor cells, such as CD163-expression, and intra-tumoral macrophage infiltration (MI) in BC are associated with early tumor recurrence and a poor prognosis." (PMID 30915533, 2019). "Here, we show that accumulation of PD-L1+ tumor and stromal cells is associated with local high infiltration of CD8+ T cells and CD68+/CD163+ TAMs." (PMID 30899426, 2019). "Conversely, in the treated patients CD163+PDL1+macrophages were significantly lower in the tumor edge and at concentration levels similar to that of the surrounding tissue." (PMID 31214178, 2019). "Vice versa, one patient in the low risk group showed a particularly low number of immune-infiltrating CD163 positive cells and tumor progression during the observation period (EFS 1.5 year)." (PMID 31239476, 2019). "Macrophages in the TME can co-express anti-tumor marker (CD169) and pro-tumor markers (CD163, CD204, and CD206)." (PMID 30999966, 2019). "Concomitant with the high levels of MGL ligands, MGL receptor expression was observed in myeloid cells in tumor stroma, more specifically in CD163+ myeloid cells." (PMID 30761272, 2019).
tumor (continued). "Meanwhile, the number of F4/80 labeled TAMs, the number of CD163 labeled M2 TAMs, and the Ki-67 index in the tumor tissues were significantly reduced in the CCR2 antagonist group than those in the control group (P < 0.01)." (PMID 31024838, 2019). "Macrophages, specifically the CD163+ ones, were predominantly found at the tumor invasive front, whereas CD80+ macrophages were almost exclusively located in the ANM, which suggests a predominant anti-inflammatory polarization of TAMs." (PMID 31481956, 2019). "Although not statistically significant, we observed a trend suggesting an inverse relationship between ER expression and CD163 expression in BC tumor cells, consistent with findings from previous studies." (PMID 30915533, 2019). "High levels of tumor-infiltrating CD68+ M, CD163+ M2, and CD47 expression were significantly associated with worse survival." (PMID 31771616, 2019). "High levels of IL10 in tumors are generally considered to reflect an immunosuppressive tumor microenvironment, which our presented data on CD163 expression and M2 macrophage polarization supported." (PMID 30879106, 2019). "The tumor stroma showed signs of a reactive response with increased type 2 (CD163+) macrophage infiltration, vascular density and hyaluronic acid, and reduced levels of caveolin-1, androgen receptors, and mast cells." (PMID 30980038, 2019). "The scavenging receptor CD163, a marker of M2 macrophages and TAMs, has been shown to promote their pro-tumor activities in mice and humans." (PMID 31878087, 2019). "We observe that the blockade of LIF in tumors expressing high levels of LIF decreases CD206, CD163 and CCL2 and induces CXCL9 expression in tumor-associated macrophages." (PMID 31186412, 2019). "Our immunocytochemical data demonstrated that CD68 and CD163 positive infiltrating cells represent the cell types actively synthesizing C1q in the tumor micro-environment." (PMID 31649675, 2019). "All studies used immunohistochemistry to detect CD68- or CD163-positive macrophages in tumor specimens." (PMID 31528210, 2019). "We found that the number of CD163+ TAMs significantly correlated with high tumour grade, high Ki-67 proliferation index and high tumour size." (PMID 30816272, 2019). "The variables of CD47 expression, CD68+ M or CD163+ M2, tumor diameter, N stage, and grade were included in the multivariate analysis." (PMID 31771616, 2019). "Double labeling experiments were also performed using an anti-CD163, a specific marker for the tumor-promoting M2-polarized macrophages." (PMID 31649675, 2019). "We detected ASC staining in tumor cells as well as in TAMs (identified by CD163 staining) within the stroma." (PMID 30760333, 2019). "In contrast, the CD68+CD163+CD206+ macrophages were furthest from the tumor cells (median distance 23.8 μm)." (PMID 31477692, 2019). "Immunofluorescence studies indicated that fewer pan macrophages (CD68+CD163+) are present in the lung of STAT6−/− tumor-bearing mice than their WT littermates." (PMID 31798581, 2019). "An increase in F4/80+ macrophages and decrease in CD163+ macrophages were observed in the tumor sections of OG-treated mice." (PMID 31905895, 2019). "CD163 was used as a marker for TAMs, and the density of TAMs in tumour nest and surrounding stroma was quantified using immunohistochemistry (IHC)." (PMID 31186031, 2019). "Since immunohistochemical stainings in serial PDAC tissue sections revealed a high abundance of CD68+ and CD163+ TAMs within tumor areas with marked PD-L1 expression, our data suggest that TAMs represent one of the PD-L1 expressing stromal populations." (PMID 30899426, 2019). "Previously, associations were reported between the MVD and the presence of tumour-associated macrophages (CD68+ cells, and CD68+CD163+ cells)." (PMID 31337000, 2019).
tumor (continued). "Stratification according to tumor stage revealed that macrophages, specifically the CD163+ ones, are more prevalent in stage II tumors, whereas CD80+ macrophages are predominant in less invasive T1 tumors." (PMID 31481956, 2019). "In the CD163+ group, 36/42 (85.7%) patients had multiple tumour nodules; in the CD163− group in 9/16 (56.3%) patients, this was diagnosed (p = 0.016)." (PMID 31170995, 2019). "For instance, both the overall survival and distant recurrence-free survival were significantly decreased in breast cancer patients with more than 25% of tumor cells CD163 positive." (PMID 30736482, 2019). "Tumor tissue derived from CT26Flag−CAGE1 cells showed higher expression of CD163, tryptase, and chymase but lower expression of iNOS than the tumor tissue derived from the CT26 cells." (PMID 31799196, 2019). "Expression of CD163 was diffusely detected in tumor stroma and around tumors, while expressions of CD204 and CD206 were mainly detected in and around tumors." (PMID 31601953, 2019). "We thus evaluated the expression of the checkpoint molecule PDL1 and the macrophage marker CD163 by image cytometry in the tumor of the enrolled patients." (PMID 31214178, 2019). "While high CD68++CD163+ TAM density proximal to the tumor correlated with improved survival in univariate analysis, this was not confirmed in a multivariate model incorporating known prognostic clinical parameters (e.g., age, tumor stage)." (PMID 31477692, 2019). "It would be important to clarify if the quantifications of CD68 and CD163 were performed in exactly the same tumor regions." (PMID 31481956, 2019). "A higher amount of CD68‐, CD163‐ and CD206‐positive GAMs in the vital tumor core was associated with beneficial patient survival." (PMID 30506802, 2019). "In our data, we found the CD68+IRF8+, CD68+CD206+, and CD68++CD163+ macrophages to be co-localized in the same tumor and were correlated with the increase of IL-1-, IL-6-, and IL-10-associated pathways, respectively." (PMID 31477692, 2019). "The relationship between the pan-macrophage marker CD68 and some other pro-tumor macrophage markers, such as CD163, CD204 and CD206, has been studied previously." (PMID 31528210, 2019). "The tumor tissue lysates of CT26Flag−CAGE1 cells revealed the activated macrophages based on the higher expression of CD163 than in CT26 tumor lysates." (PMID 31799196, 2019). "Consistent with previous reports, CD68, CD163, and CD14 antibodies strongly stained cells in the CHL tumor microenvironment in each of the variants." (PMID 31714922, 2019). "In the control untreated patients, PDL1 was mostly confined in CD163+macrophage at the tumor edge whereas tumor and normal surrounding tissues expressed low level of this protein." (PMID 31214178, 2019). "With increasing proximity to tumor cells, an increase in CD163 expression was observed in all CD163+ macrophages." (PMID 31477692, 2019). "Altogether, the data demonstrate higher densities and closer proximities of CD68+ and CD163+ pixels in tumor and T cell regions compared to CD11b+ and CD11c+ pixels." (PMID 30619287, 2018). "In all three cases, the vast majority of CD163(+) cells in tumor tissues were derived from bone marrow." (PMID 30272010, 2018). "We observed that Sema4D is positive in cells bearing the monocytic/macrophage marker CD163, indicating that Sema4D is positive in the macrophage lineage of the tumor microenvironment." (PMID 29541402, 2018). "There were significantly more iNOS+/CD86+ cells in high PKN2 expression tumor tissues, while the number of CD206+/CD163+ cells was significantly higher in low PKN2 expression tumor tissues." (PMID 29368606, 2018). "Further, the IBA1+ and CD163+ immune brain cells express EGF in the tumor border and thus stimulate the tumor cells to invade the parenchyma." (PMID 30123112, 2018).